PER1 (period circadian regulator 1)
Diseases named in the same sentence as PER1 in open-access papers (continued):
Sharing a sentence is not in itself a finding about the gene and the disease.
cancer (continued). "Recent studies have showed aberrant expressions and altered rhythms of PER1 were highly correlated to the carcinogenesis and development of malignant tumors." (PMID 23405233, 2013). "Aberrant PER1 expression can easily lead to abnormal cell proliferation and the basic characteristic of malignant tumor is its uncontrolled and disordered cell proliferation." (PMID 23405233, 2013). "At the molecular level, Per1 and Per2 are involved in the DNA damage response, and overexpression of either protein inhibits cancer cell growth and increases the apoptotic rate, supporting the notion that they participate in tumor suppression." (PMID 23563360, 2013). "We found that when kept in 24 hour alternating light-dark conditions (24hr LD cycles), mice deficient in Bmal1 (Bmal1+/−), Cry1 and Cry2 (Cry1−/−;Cry2−/−), Per1 and Per2 (Per1−/−;Per2m/m) or Per2 alone (Per2−/−) were all cancer-prone." (PMID 20539819, 2010). "More specifically, circadian rhythm genes (PER1 in particular) play important roles in cell cycle regulation and cancer processes." (PMID 20168994, 2010). "Per1 overexpression in cancer cells increases ionizing radiation-induced apoptosis, whereas inhibition of Per1 in similarly treated cells blunts apoptosis." (PMID 20353609, 2010). "Starting from the biological functions of PER1, this article reviews its roles, pathophysiological significance, and related molecular mechanisms in cardiovascular diseases, neurodegenerative diseases, metabolic disorders, immune-related diseases, and cancer." (PMID 41451215, 2025). "This suggests that the overexpression of PER1 may enhance the sensitivity of human cancer cells to DNA damage-induced apoptosis, while its inhibition weakens the apoptotic response." (PMID 39456709, 2024). "In contrast, an anti-apoptotic role of PER1 has been observed in various human cancer cell lines." (PMID 38245510, 2024). "Overexpressed PER1 also induces c-Myc and suppresses p21, while other studies have reported that PER1 inhibits Cyclin B1, Cdc2 and Wee1 expression, leading to a decrease in cancer cell proliferation." (PMID 36768253, 2023). "The search for therapeutic targets aimed at glycolysis of cancer cells has shown great prospects for the development of cancer treatments; however, it is currently unclear whether PER1 can regulate glycolysis in cancer cells." (PMID 33723221, 2021). "Indeed, apoptotic regulators DEC1 and DEC2 repress CLOCK/BMAL-induced transactivation of the PER1 promoter and modulate the response to cisplatin in several types of cancers, including human eSCC cell lines." (PMID 33810377, 2021). "Heterozygous deletion of PER1 also has been observed in cancer." (PMID 34566638, 2021). "An anti-apoptotic role of PER1 has been described in different human cancer cell lines." (PMID 33804124, 2021). "PER1 is downregulated in many types of cancers in the Cancer Genome Atlas." (PMID 34566638, 2021). "Low expressions of Per1 and Per2 could serve as unfavorable indicators for cancers prognosis, especially for gastrointestinal cancers." (PMID 32437452, 2020). "Furthermore, the results revealed that low expressions of Per1 and Per2 were also correlated with poor overall survival of cancers (Per1: HR=1.35, 95%CI: 1.06∼1.72, P=0.014; Per2: HR=1.43, 95%CI: 1.10∼1.85, P=0.007)." (PMID 32437452, 2020). "Meanwhile, others clock genes were downregulated including PER1 in 11 cancer types, PER2 in 7, PER3 and CRY2 in 10 and RORα in 11, indicating they may act as tumor suppressor genes." (PMID 33042011, 2020). "Moreover, PER1 interacts with proteins involved in DNA damage response and PER1 overexpression has been shown to suppress the growth of human cancer cell lines." (PMID 32244760, 2020).
cancer (continued). "However, well designed, larger-size and higher-quality cohort studies are needed to investigate the precise impact of Per1, Per2and Npas2 on the pathobiological behaviors and prognosis of cancers." (PMID 32437452, 2020). "Moreover, despite the expansive knowledge of Per1 and Per2 roles in cancer cells, their roles in the TME were largely overlooked." (PMID 33123539, 2020). "Furthermore, hypermethylation of PER1/PER2/PER3 was observed in most cancers, although the hypermethylation of PER3 was only statistically significant in HNSC, BRCA, and THCA." (PMID 30791227, 2019). "Overexpression of clock gene Per1 in human cancer cell lines led to significant growth reduction following ionizing radiation, whereas mouse cell lines mutated in clock genes were indistinguishable from wild-type ones in their response to ionizing radiation and other DNA damaging agents." (PMID 28466226, 2017). "Our study clarifies that PER1 has an important role in regulating the clock gene network, and for the first time finds that the regulation function has a large difference between normal cells and cancer cells." (PMID 27602964, 2016). "We determined that the mRNA expression of TIM was increased after PER1 knockdown in cancer cells, indicating that TIM may either serve as a factor in the circadian feedback loops of cancer cells." (PMID 27602964, 2016). "Although it has been reported that Per1 has an important role in the cell cycle and apoptosis in cancer cells, the increase in KCs may also be attributed to the influence of Per1 on proliferation and/or apoptosis in macrophages." (PMID 27054331, 2016). "At present, it is recognized that altered PER1 expression could result in altered expression of downstream cell cycle genes and cancer-related genes, thus leading to the occurrence of tumors." (PMID 27602964, 2016). "The expression of clock gene PER1 is decreased in many types of cancer." (PMID 27602964, 2016). "This study demonstrates that the down-regulation of PER1 in cancer cells can result in the robust up-regulation of PER3, TIM, RORα and REV-ERBα transcripts, while the expression of PER2, DEC1, DEC2, CRY1, CRY2 and NPAS2 is prominently down-regulated in vitro and in vivo." (PMID 27602964, 2016). "Quantitative real-time PCR result indicated that in vitro and in vivo cancer cells after PER1 knockdown, PER2, DEC1, DEC2, CRY1, CRY2 and NPAS2 were significantly down-regulated at the mRNA level, while PER3, TIM, RORα and REV-ERBα were significantly up-regulated." (PMID 27602964, 2016). "In addition, Per1 and Per2 have been reported to be downregulated in several human cancers, and overexpression of either gene inhibits the growth of cancer cells." (PMID 25760074, 2015). "Per1 and Per2 are relatively well characterized in terms of their roles in cancer." (PMID 23563360, 2013). "Moreover, the study reveals that aberrant acetylation of Per1 promoter is also a potential mechanism for silencing Per1 in cancer." (PMID 20353609, 2010). "However, the drug target role of PER1 in cancer remains a subject of debate." (PMID 38245510, 2024). "Thus, PER1 promotes the growth of cancer cells in vitro and tumors in vivo." (PMID 38892035, 2024). "When over-expressed, PER1 was shown to set off apoptosis associated with DNA damage and altered expression of critical cell cycle controllers, such as WEE-1, Cyclin B1, and CDC2 in various human breast (MDAMB-231), colon (SW48), lung (NCI-H460), and endometrial (Ishikawa) cancer cell lines." (PMID 34440260, 2021). "Therefore, although heterogeneity existed, these pooled results suggested that low expressions of Per1, Per2, Per3 and Npas2 might play important roles in the development and progression of cancers." (PMID 32437452, 2020).
cancer (continued). "Hence, we speculate that the lower expression of PER1 in cancer cells can influence the activation and the intracellular distribution of CLOCK/BMAL1, rather than the alteration in expression level." (PMID 27602964, 2016). "However, it is still unclear whether the lower expression of PER1 in cancer can influence the expression of other clock genes in the clock gene network." (PMID 27602964, 2016). "However, it is still unclear whether reduced PER1 expression in carcinoma cells can affect the normal expression of other clock genes in the inherent network." (PMID 27602964, 2016). "Also consistent with Per1, the genes induced by Per2 overexpression did not include putative atrophy associated genes such as Murf1 or Mafbx or those shown to be altered by Per2 induction in cancer cells." (PMID 40632504, 2025). "The inhibition of CK1δ using PF-670462 has shown potential in reducing PER1, PER2, and other clock genes in rats and is suggested as a cancer therapeutic agent." (PMID 40002179, 2025). "Emerging evidence suggests that alterations in clock genes, including the PER gene family (PER1, PER2, and PER3), play a significant role in cancer development and progression due to their regulatory functions in biological cycles and physiological processes." (PMID 38813085, 2024). "On comparison of the expression of PER1, AKAP12, and MMP17 in TCGA with that in the GTEx dataset, the levels of the three genes were higher in normal ovarian tissues than in cancer tissues." (PMID 37434173, 2023). "As TIMELESS expression was significantly upregulated and RORA, PER1, PER2, and CRY2 expression was significantly downregulated in most cancer types including LUAD and LUSC, it is necessary to probe their prognostic values." (PMID 35078435, 2022). "GEPIA was used to understand the messenger (m)RNA expressions of circadian rhythm-related factors in the PER family (PER1, PER2, and PER3), CRY family (CRY1 and CRY2), BMAL1, and CLOCK in different types of cancer." (PMID 36385012, 2022). "In our study, PER1 silencing smoothed back changes of fundamental molecular factors controlling the cell cycle, apoptosis, DDR, EMT, and autophagy, involved in cancer onset and development." (PMID 34440260, 2021). "In this study, we investigated the expression of PER1 in OV tissues and adjacent normal tissues based on the TIMER and Oncomine databases and found that its expression in cancer tissues was lower than that in normal tissues." (PMID 34220965, 2021). "Consistently, PER1 overexpression and subsequent activation of downstream ATM-Chek2 signalling has been proved to suppress the growth of multiple human cancer cell lines by inducing G2/M cell cycle arrest." (PMID 32429928, 2020). "Inhibition of endogenous Per1 expressionresulted in the abrogation of the ATM/Checkpoint kinase 2 (Chk2) checkpoint pathway and led to less DNA damage-induced apoptosis of cancer cells." (PMID 32437452, 2020). "The period genes PER1 and PER3 have been found to suppress cancer cell growth and have also been observed to be deregulated in breast cancer." (PMID 31949161, 2020). "A deceased expression of PER1 and/or PER2 has been reported in numerous cancers: breast tumor, prostate tumor, pancreatic tumor, colorectal tumor, chronic myeloid leukemia, glioma, and intestinal epithelial neoplastic transformation." (PMID 31803621, 2019). "Among 716 samples across 29 cancer types, we interestingly observe that most of the negative regulators, such as PER1, PER2, PER3, CRY1, CRY2, and NR1D2, are down-regulated in a wide range of cancers." (PMID 31708917, 2019).
cancer (continued). "In contrary, the overexpression of these PER (e.g., PER1) proteins lead to inhibition of cancer cells growth in vitro and in vivo, and sensitization of cancer cells to DNA damage-induced apoptosis." (PMID 26927666, 2016). "In our research, mRNA expression of NPAS2 was robustly decreased after PER1 knockdown, indicating that the compensatory effect on CLOCK/BMAL1 was weakened due to PER1 knockdown in cancer cells." (PMID 27602964, 2016). "proved that promoters of these clock genes (PER1, PER2, PER3, CRY1 and CRY2) were methylated in a variety of cancer cells, which resulted in their decreased expression." (PMID 27602964, 2016). "We showed that PER1, PER2, and PER3 gene expression levels were all lower in cancer tissue than in liver tissue, while CSNK1E gene expression was higher in cancer tissue." (PMID 27492458, 2016). "Several of the direct FOXP1 targets upregulated in response to cancer were transcriptional repressors of the circadian clock, including Kfl9, Nr1d1, Per1, and Bhlhe40, providing further evidence that FOXP1 is a negative regulator of clock function in skeletal muscle in response to cancer." (PMID 40349340, 2025). "Specifically, PER1 interacts with PPARγ to enhance its transcriptional activity, promoting HK2 expression, altering glucose metabolism, and impacting the proliferation and survival of cancer cells." (PMID 40243466, 2025). "Because PER1 and PER2 are involved in the DNA damage response pathways, abnormal expressions of them may result in cancer." (PMID 38892035, 2024). "However, in other human cancer cell lines, such as CA9-22 pancreatic cancer cells, MTA PCa-2 prostate cancer cells, and HepG2 liver cancer cells, PER1 exhibits anti-apoptotic properties." (PMID 39456709, 2024). "For example, low PER1/PER2 expression in different types of cancer, such as breast, glioma, gastric and non-small cell lung cancer, is closely related to the development and metastasis of tumors." (PMID 36768253, 2023). "In addition, it was shown that Cluster 1 (CRY2, PER1, and RORA) and TIMELESS exerted opposite impacts on interactive gene network, infiltration of immune cells, cancer-related signaling pathways, and cellular sensitivity to clinically used drugs." (PMID 34745328, 2021). "Besides, CRY2, PER1, and RORA exerted opposite impacts against TIMELESS on immune cell infiltration and cancer-related signaling pathways, affecting the overall survival of HCC patients." (PMID 34745328, 2021). "The association between PER1 and PER3 mRNA expression levels and cancer prognosis was not meta-analyzed as the number of experimental studies was <3." (PMID 32849922, 2020). "DNA methylation data were available only for PER1/2/3 and ARNTL, and the analysis showed that the promoter regions of PER1/2/3 and ARNTL were generally highly methylated in most cancers and that the expression level and methylation status were highly correlated." (PMID 30791227, 2019). "We also illustrated that PER1 knockdown in OSCC cells SCC15 results in altered expression of numerous downstream cell cycle genes and cancer-related genes, which enhanced proliferation and metastasis of cancer cell." (PMID 27602964, 2016). "Their functional effects on cancer prognosis could also be of interest since both PER1 and PER3 belong to core circadian genes, which are involved in cancer development and progression." (PMID 26927666, 2016). "We suggest that down-regulated PER1 expression was correlated with more advanced cancer stages in patients with BSCC, implying that PER1 is an anti-oncogene and its expression may mainly correlate with the invasion and metastasis of BSCC cells." (PMID 23405233, 2013). "Notably, the genes induced by Per1 overexpression did not include putative atrophy associated genes such as Muscle Ring Finger 1 (Murf1) or Muscle Atrophy F-box (Mafbx), nor did it include pathways shown to be altered by Per1 induction in cancer cells." (PMID 40632504, 2025).
cancer (continued). "In order to achieve a systematic understanding of circadian clock in cancer, we define a core subset of clock family genes including 7 positive regulators (CLOCK, NPAS2, ARNTL, ARNTL2, RORA, RORB, and RORC) and 7 negative regulators (PER1, PER2, PER3, CRY1, CRY2, NR1D1, and NR1D2)." (PMID 31708917, 2019). "Furthermore, long-term observations of animals with single or double deletions of clock genes such as Per1,2−/− and Cry1,2−/− or mice lacking a single copy of Bmal1, revealed them to be cancer-prone." (PMID 28425940, 2017). "In conclusion, our study demonstrated that the expression of clock gene PER1 was significantly down-regulated in cancerous tissues compared to adjacent noncancerous tissues of patients with BSCC and decreased PER1 expression was correlated with more advanced cancer stages." (PMID 23405233, 2013). "PER1, PER2, and PER3 protein expression levels can be used as novel potential biomarkers for predicting cancer prognosis." (PMID 32849922, 2020). "A significant negative correlation was also found between PER1/PER2 activity and VEGF expression in ESCC patients’ cancer tissue, showing that decreased levels of PER1/PER2 may influence VEGF levels." (PMID 31151182, 2019).
infection (9 papers, 2006 to 2025). The state of being infected such as from the introduction of a foreign agent such as serum, vaccine, antigenic substance or organism. "On the other hand, Per1, also induced upon challenge, inhibits recruitment of Gr1-positive/Ccr2-expressing myeloid cells; interestinlgly, mainly neutrophils were affected, thus reducing host susceptibility, and mostly controling the immunopathology caused by infection." (PMID 41208953, 2025). "Though this may be related to the low number of BSI cases investigated by us, the Turkish study investigated infections of different body sites comparing those caused by PER-1-positive isolates with those produced by Pa strains with variable resistance profiles." (PMID 16542460, 2006). "The upregulation of genes Per1 and Ciart, which are involved in circadian rhythms, is striking in the absence of a large number of other transcriptional changes in response to infection." (PMID 40099884, 2025). "The only two genes upregulated more than 2-fold upon infection in HSP mutant brains are both involved in regulating circadian rhythms (Per1 and Ciart)." (PMID 40099884, 2025). "U343 cells were exposed to 6 mV 10 Gy X-ray irradiation after infection with an shRNA lentivirus to reduce the expression of PER1 and were analyzed by SCGE analysis, flow cytometry, qRT-PCR, and western blotting." (PMID 31350984, 2019). "Meanwhile, we observed that certain biomarkers (SLC7A5, PDE4D, CXCR4, PER1, PIK3R1, HBA1, HBB) were elevated during the pre-infection phase (LTBI), while others (SOCS3, GZMK, HIS1H3B) were upregulated in the post-infection phase (ATB)." (PMID 40589756, 2025). "The daytime point of infection coincides with high levels of STAT3 protein and of clock genes Per1, Per2 and Nr1d1 mRNAs, and was chosen to deduce a possible LPS-induced decrease of their levels." (PMID 30265676, 2018). "The results of this study demonstrated high prevalence of PER-1 and VEB-1 type ESBLs among A. baumannii isolates in the study region and reminded the necessity of appropriate infection control strategy to prevent further spread of infection by these organisms." (PMID 23997900, 2013). "Then we examined the protein level of Per1 24 h post-infection by western blot and found silencing pgrp-la did not impact the protein level of Per1." (PMID 31907025, 2020). "Interestingly, the per-1 ortholog (dubbed ALB1) in M. oryzae is involved in melanization of appressoria, specialized infection structures for plant infection, indicating that fungal pigments are produced in tissue-specific manners and have evolved to have divergent roles." (PMID 35638737, 2022). "Chance of developing hospital-acquired BSI and greater mean length of hospital stay (MLHS) might be related to infection by PER-1-positive strains, though differences were not statistically significant (P = 0.07 and P = 0.09, respectively)." (PMID 16542460, 2006). "Though combination therapy is usually recommended for severe Pa infections, three patients affected by BSI due to PER-1-Pa isolates failed to respond to carbapenems plus amikacin." (PMID 16542460, 2006).